TNF (tumor necrosis factor)
Diseases named in the same sentence as TNF in open-access papers (continued):
Sharing a sentence is not in itself a finding about the gene and the disease.
osteomyelitis (21 papers, 2010 to 2026). An acute or chronic inflammation of the bone and its structures due to infection with pyogenic bacteria. "Simultaneously, serum samples of S. aureus induced osteomyelitis rats were collected to assay the concentration of TNF-α and IL-10 at 1, 2, 3, 5, and 7 days through enzyme-linked immunosorbent assay (Elisa)." (PMID 36109760, 2022). "Genetic studies in osteomyelitis have suggested that certain polymorphisms in genes associated with immune modulation, such as those encoding cytokines (e.g., IL-1, IL-6, TNF-α), may affect disease susceptibility, progression, and response to treatment." (PMID 40142310, 2025). "Protection from death of rabbits with osteomyelitis was associated with attenuation of pro-inflammatory responses of E. coli sepsis as reflected by decreased production of TNFα by circulating PBMCs and by decrease of neutrophil inflammation in both the infected kidney and remote organs." (PMID 31992837, 2020). "Notably, CNO should be considered in the differential diagnosis of adult patients with long disease course and recurrent multifocal osteomyelitis of unknown cause, and these patients might benefit from combination therapy containing TNFα inhibitors." (PMID 35422809, 2022). "In the case of osteomyelitis, key SNPs within genes such as IL-1β (including rs1143634 and rs16944), IL-6 (e.g., rs1800795), VDR, and TNF-α are instrumental in evaluating susceptibility." (PMID 39301021, 2024). "The serum of osteomyelitis patients included high levels of inflammatory mediators such TNF-α and IL-1, which mediated enhanced MMP expression." (PMID 39301021, 2024). "Cytokines and chemokines play a notable role in the pathogenesis of both diseases, such as neutrophils, IL8, IL-27, IL23, MMPs, and serum TNF, which play a key role in the pathogenesis of osteomyelitis and DFU." (PMID 37904457, 2023). "More importantly, IL-1β, IFN-γ, and TNF-α were both elevated in osteomyelitis sera and their receptors in DFU." (PMID 37904457, 2023). "A recent study described a novel signaling cascade comprising TNF-α/miR-129-5p/endothelial nitric oxide synthase (eNOS) in the pathogenesis of osteomyelitis." (PMID 36483565, 2022). "Proinflammatory cytokines such as interleukin 1 (IL-1), interleukin 6 (IL-6), or tumor necrosis factor alpha (TNF-α), are produced in S. aureus-induced osteomyelitis." (PMID 31832182, 2019). "In accordance, immunofluorescence analysis revealed TNFα expression in F4/80-positive macrophages in osteomyelitis mice treated with alendronate, suggesting an association of alendronate treatment with TNFα expression." (PMID 28387378, 2017). "Additionally, medications like infliximab and adalimumab, which serve as TNF-α inhibitors, have demonstrated efficacy in managing osteomyelitis and mitigating inflammatory responses." (PMID 39301021, 2024). "In this respect, several preclinical and clinical observations indicate that osteomyelitis is accompanied by alterations in the local and (sometimes) systemic levels of both pro-inflammatory (e.g., IL-6, IL-1α, TNF-α, IL-1β) and anti-inflammatory (e.g., TGF-β1) cytokines." (PMID 36483565, 2022). "Previous studies have confirmed that RANKL/OPG signaling, TNF and TNF receptor superfamily, and the NF-kB signaling pathway play important roles in osteomyelitis in S. aureus infection, and other studies also demonstrated that curcumin can inhibit NF-κB signaling pathway." (PMID 36212814, 2022). "Accordingly, the TNF-⍺/miR-129-5p/eNOS signaling pathway is a molecular mechanism that deserves further examination to understand its impact on the pathology of S. aureus-induced osteomyelitis." (PMID 35011442, 2021). "TNF-α is a widely known key player in the pathogenesis of osteomyelitis." (PMID 34083570, 2021).
osteomyelitis (continued). "Osteomyelitis was an essential part of bone infection disease and characterized by a severe inflammatory reaction that contributed to bone destruction due to the release of pro-inflammatory cytokines (TNF-α, IL-1β and IL-6) from many bacterial." (PMID 32527985, 2020). "Furthermore, proinflammatory cytokines, such as TNF-α, are known to be produced in S. aureus-induced osteomyelitis, which in turn, results in progressive inflammatory destruction of the bone." (PMID 31832182, 2019). "Toxin secretion such as interleukin (IL)-1, IL-6 and tumor necrosis factor (TNF)-α may produce S. aureus-induced osteomyelitis and stimulate bone resorption." (PMID 23251279, 2013). "Inflammatory markers, such as interleukin-6 (IL-6), tumor necrosis factor-alpha (TNF-α), procalcitonin (PCT), and C-reactive protein (CRP), serve as pivotal indicators in assessing the severity of osteomyelitis." (PMID 40956854, 2025). "The findings suggest potential linkages between SNPs in genes such as IL-1, IL-6, IFN-γ, TNF-α, VDR, tPA, CTSG, COX-2, MMP1, SLC11A1, Bax, NOS2, and NLRP3 with the development of osteomyelitis." (PMID 39301021, 2024). "Briefly, TNF-α and miR-129-5p were upregulated while eNOS was downregulated in S. aureus-infected MC3T3-E1 cells and in osteomyelitis patients’ blood." (PMID 36483565, 2022). "Current research has amassed increasing evidence suggesting that SNPs in various genes, including IL-1, IL-6, IFN-γ, TNF-α, VDR, tPA, CTSG, COX-2, MMP1, SLC11A1, Bax, NOS2, and NLRP3, may contribute to the development of osteomyelitis." (PMID 39301021, 2024). "Other studies investigating these cytokines in osteomyelitis found increased TNFα in the early stage of chronic osteomyelitis rather than the late stage." (PMID 34831397, 2021). "Another study involving the stimulation of blood from patients with osteomyelitis with lipid polysaccharides (LPS) did not affect the expression of TNFα or other cytokines in the blood." (PMID 34831397, 2021).
TB meningitis (21 papers, 1994 to 2025). "Related results have been found in patients with underlying TB meningitis, who after six months of antibiotic therapy presented elevated levels of TNF and IFN-γ, indicating the persistence of neuroinflammation." (PMID 37375056, 2023). "It has been demonstrated that elevated levels of TNF are associated with TB meningitis and tuberculoma." (PMID 28280495, 2017). "Importantly, corticosteroids that are routinely given in conjunction with antibiotics to all patients with TB meningitis, in an attempt to reduce inflammation-related sequelae, have recently been shown to benefit only those TB patients predisposed to overproduce TNF." (PMID 23762096, 2013). "Another study has proved that Escherichia-Shigella is the dominant bacteria in the gut microbiome, and its abundance is positively correlated with the level of TNF-α in patients with tuberculous meningitis." (PMID 37846989, 2023). "Associations of cerebrospinal fluid (CSF) tryptophan with IFN-γ (A) and with TNF-α (B) in 176 Indonesian (left) and 304 (Vietnamese) tuberculous meningitis (TBM) patients." (PMID 37158692, 2023). "Among patients with tuberculous meningitis, different inflammatory patterns governed by host genetics are recognized, converging on dysregulated levels of TNF." (PMID 29375567, 2017). "In an elegant translational component of their study, they demonstrated that among patients with tuberculosis meningitis, only those with the high- TNF-α producing genotype benefited from the standard addition of corticosteroids to their therapeutic regimen." (PMID 24586159, 2014). "Recently, the benefit of steroids for TB meningitis in adolescents and adults was found to be limited exclusively to a subset of individuals with a genetic propensity to produce high levels of TNF." (PMID 23762096, 2013). "The local production of tumour necrosis factor-α (TNFα)was evaluated in the cerebrospinal fluid (CSF) from ten patientswith tuberculous meningitis (TBM)." (PMID 18472925, 1994). "Furthermore, in another study on the Asian population, Escherichia/Shigella genera were found to be dominant in patients with TB meningitis while correlating with elevated plasma tumor necrosis factor-alpha (TNF-alpha)." (PMID 41231796, 2025). "Compared to Human Immunodeficiency Virus(HIV)–infected patients without central nervous system involvement, HIV-associated tuberculous meningitis patients exhibited elevated levels of T-helper factor (Th) 17, TNF-α, and LT." (PMID 38835752, 2024). "Because infants have an inherently restricted capacity to produce TNF, infants are unlikely to have TB meningitis that is caused by a hyperinflammatory state." (PMID 23762096, 2013). "This raises the question as to whether adjunctive steroid therapy should be given to infants with TB meningitis, because steroid therapy in adolescents and adults only benefits those with a propensity to produce high amounts of TNF." (PMID 23762096, 2013). "However, the BBB disruption detected in TB meningitis was shown to be related to vascular endothelial growth factor (VEGF) and tumor necrosis factor alpha (TNF-α)." (PMID 26440149, 2015). "In TB meningitis patients who produce low amounts of TNF, corticosteroids are not helpful and may even be detrimental." (PMID 23762096, 2013).
Ureteral obstruction (21 papers, 2012 to 2025). Obstruction of the flow of urine through the ureter. "The P2X7R promotes the release of IL-6 and TNF from mouse microglia, which are implicated in tubular fibrosis and apoptosis in response to ureteral obstruction in mice." (PMID 35530034, 2022). "For example, ureteral obstruction caused a significant upregulation of the mRNA expression of TNF-α, PAI-1, IL-6, and IL-1β (2.22 ± 0.47 vs. 1.03 ± 0.11, 5.38 ± 0.87 vs. 1.02 ± 0.10, 10.35 ± 1.42 vs. 1.00 ± 0.21 and 1.55 ± 0.07 vs. 0.99 ± 0., respectively, p < 0.05 for all)." (PMID 39457599, 2024). "In the absence of MFAP4, downregulation of pro-inflammatory cytokines (IL-1β and TNF-α) and concurrent inhibition of NF-κB signaling pathway activation can mitigate the inflammatory response induced by unilateral ureteral obstruction." (PMID 39508749, 2025). "Previous studies have shown that ischemia, hypoxia and TNF‐α together contribute to pathophysiological changes in the kidneys following ureteral obstruction and FA treatment in vivo." (PMID 39566909, 2025). "In tubulopathy and interstitial fibrosis secondary to the ureteral obstruction, the production of reactive oxygen species (ROS) in the kidney and an increase in the renal expression of TNF-α have a pivotal role." (PMID 38962754, 2024). "Conversely, the inhibition of TNF downstream effector interleukin 1β increases the Aqp2 gene expression under ureteral obstruction conditions." (PMID 35685285, 2022). "A study showed that the expression of IL-1β, IL-6, IL-18, and TNF-α in peripheral blood and renal tissues of rats with unilateral ureteral obstruction was significantly reduced by DSF." (PMID 35563653, 2022). "It was also shown that conditional knockout of TGF-βRII in renal tubular cells exhibited increased renal inflammation with up-regulation of interleukin-1β (IL-1β) and tumor necrosis factor-α (TNF-α) after induction of ureteral obstruction." (PMID 30150520, 2018). "Furthermore, melittin has been shown to reduce TNF-α and IL-1β expression in chronic kidney injury models, such as unilateral ureteral obstruction, highlighting its broad anti-inflammatory efficacy across different etiologies of renal injury." (PMID 41301702, 2025). "After the onset of unilateral ureteral obstruction, IL-10 knockout mice show increased infiltration of inflammatory cells and cytokines, including monocyte chemoattractant protein-1, TNF-α, IL-6, IL-8, RANTES, or macrophage colony-stimulating factor, in the kidney compared with WT controls." (PMID 31194740, 2019). "Unilateral ureteral obstruction (UUO) in the neonatal mouse caused renal structural injury, induced key molecules of the necrosome (RIPK3 and phospho-MLKL) and generated inflammatory cytokines (IL-1α, INF-γ and TNF-α) in the neonatal kidney." (PMID 31819111, 2019). "In kidneys of mice with ischemia-reperfusion injury or unilateral ureteral obstruction, the loss of ACE2 exacerbated infiltration of neutrophils, F4/80+ macrophages, and CD3+ T cells, and increased mRNA levels of cytokines and chemokines, including IL6, TNF, and MCP-1." (PMID 33125431, 2020). "For instance, in the unilateral ureteral obstruction (UUO) model, melittin significantly inhibited inflammation and fibrosis by downregulating TGF-β1 and TNF-α–mediated pathways." (PMID 41301702, 2025). "An increase in histone H3 acetylation during ureteral obstruction in young rats may be caused by the activation of NF-kB and the recruitment of HAT-coactivators p300/CBP, which may be confirmed by a decrease in H3 acetylation and TNF-α expression upon inhibition of p300 in the UUO model." (PMID 41154528, 2025). "By qRT-PCR, we found that the inflammatory markers TNF-α, IL-1β, and ICAM-1 were markedly elevated following 7-day ureteral obstruction, and such increments were robustly abolished or attenuated by rotenone administration." (PMID 25140114, 2014).
Ureteral obstruction (continued). "mRNA expression of IL1α, IL1β and IL18 but not of TNFα increased in response to ureteral obstruction (D and C correspondingly)." (PMID 37553369, 2023). "In support of this hypothesis, we have recently demonstrated that the inhibition of STAT3 by S3I-201 suppressed the expression of TNF-alpha, IL-1beta, and ICAM-1 without affecting that of MCP-1 in the mouse kidney injured by ureteral obstruction." (PMID 22558380, 2012).
abdominal aortic aneurysm (20 papers, 2009 to 2025). Enlargement and ballooning of the vessel that supplies arterial blood to the abdomen, pelvis and legs. "The incidences of post-implantation syndrome vary widely between 14% and 60% for abdominal aortic aneurysm and intervention was suggested to cause white cell activation with the release of various cytokines, such as IL-1, IL-6, and TNF-α." (PMID 22655044, 2012). "Similarly, in the context of Trem-1−/− with angiotensin-II induced abdominal aortic aneurysm, inflammation and aortic wall degradation were markedly reduced, which was associated with decreased expression of Il1b, TNF-α, MMP2, and MMP9." (PMID 41226426, 2025). "Formerly, it was elaborated that miR-155 triggers expression of macrophages and cytokines; TNFα, and IL-6 in abdominal aortic aneurysm in mice, and there was a significant positive correlation among the three of them." (PMID 39798064, 2025). "The study established an elastase-induced mouse abdominal aortic aneurysms model as well as a TNF-α-mediated vascular smooth muscle cells (VSMCs) model, respectively." (PMID 36209172, 2022). "TNF-α released by activated monocytes, are found in atherosclerotic plaques and in significantly greater levels in abdominal aortic aneurysm, which can enhance ICAM-1 expression on endothelial cell cultures in vitro." (PMID 28069066, 2017). "Glutamine protected against mouse abdominal aortic aneurysm through inhibiting M1 macrophage activation, secretion of IL-6 and TNF-α by macrophage, release of MMP-9 by RAW264.7 (macrophage) and MMP-2 by MOVAS (SMC), as well as apoptosis of vascular SMC by ROS and MMP." (PMID 38903916, 2024). "TG2 has been shown to inhibit MMP-2, -9, and tumor necrosis factor (TNF)-α in primary cultures of human abdominal aortic aneurysm-derived smooth muscle cells, supporting the notion that TG2 stabilizes the ECM and prevents the progression of abdominal aortic aneurysm." (PMID 39744707, 2024). "Also, microRNA(miR)-195 suppressed abdominal aortic aneurysms through the TNF-α/NF-kB and VEGF/PI3K/Akt pathway." (PMID 38137108, 2023). "Tumor necrosis factor (TNF) is pathologically elevated in human abdominal aortic aneurysms (AAA)." (PMID 36186984, 2022). "Also, our study confirmed that the expression of inflammatory factors IL-6, IL-17, and TNF was significantly increased in abdominal aortic aneurysm samples compared with adjacent aorta samples." (PMID 33362847, 2020). "In a mouse model of abdominal aortic aneurysm induced by intraluminal elastase and extraluminal calcium chloride exposure in vivo, TG2, TNF-α, MMP-2, and MMP-9 mRNA expression were increased in the acute phase compared to the chronic phase of the disease." (PMID 39744707, 2024). "In a model of CaCl2 induced abdominal aortic aneurysm, BRG1 mediates TNF-α induced transcription of colony stimulating factor (CSF1) in endothelial cells to stimulate macrophage trafficking." (PMID 32733885, 2020). "In addition, a recent study noted that knockdown of PVT1 decreased levels of MMP-2 and MMP-9, augmented TIMP-1 expression, and suppressed serum levels of TNF-α, IL-1β, and IL-6 in VAMC and ApoE-/- mice of abdominal aortic aneurysm model." (PMID 34775377, 2021). "The role of the TNF-p55 TNFR signaling in the development of abdominal aortic aneurysms is not defined." (PMID 19582157, 2009).